AR (androgen receptor)
Diseases named in the same sentence as AR in open-access papers (continued):
Sharing a sentence is not in itself a finding about the gene and the disease.
prostate adenocarcinoma (180 papers, 2005 to 2026). "Salivary duct carcinoma (SDC) is an aggressive AR + tumor with a high propensity for early metastasis, whereas low-risk prostate adenocarcinomas (PCa) are often indolent." (PMID 41971061, 2026). "Regarding the Hormone_ER and AR signatures, these are particularly relevant to hormone-sensitive cancers, such as BRCA and PRAD (prostate adenocarcinoma), given their association with estrogen receptor (ER) and androgen receptor (AR) activity." (PMID 40002821, 2025). "SPOP, a frequently mutated E3 ubiquitin ligase in PCa, can bind to and ubiquitinate AR in prostate adenocarcinoma cells, while prostate adenocarcinoma-associated SPOP mutations abolish this activity." (PMID 38275816, 2024). "Various factors have been implicated in the onset and progression of NED in prostate adenocarcinomas, such as androgen receptor (AR) loss, conventional therapy, and cytokine dysregulation." (PMID 39682758, 2024). "While adenocarcinoma of the prostate is canonically associated with AR positivity, urothelial carcinoma of the bladder also expresses the AR protein, as demonstrated by several early studies." (PMID 38398136, 2024). "About 50% of CRPCa cases retain the characteristics of prostate adenocarcinoma (AdPCa), expressing markers associated with the luminal epithelia of the prostate, such as androgen receptor (AR), AR targets, and HOXB132,3." (PMID 39095562, 2024). "Elevated CDK19 expression was associated with those prostate adenocarcinoma cell lines that express AR at a high level." (PMID 38546787, 2024). "We have also shown that fimepinostat suppresses the activities of Myc and AR, including AR variants resulting from mRNA splicing or structural alterations, by inhibiting HDACs and disrupting the transcription of these genes in prostate adenocarcinoma." (PMID 37823778, 2023). "The AR-V7 androgen receptor variant described in prostate adenocarcinoma causes resistance to anti-androgenic treatment." (PMID 35739348, 2022). "The underlying initiator of PCa, the androgen receptor, is the driver of prostate adenocarcinoma development, can be visualized with [18F]-FDHT." (PMID 32582550, 2020). "Loss of REST is a key factor for prostate adenocarcinoma cells to gain NE phenotypes under various conditions, including AR inhibition." (PMID 29156689, 2017). "In addition, although LNCaP cells are typical of conventional adenocarcinoma of the prostate, the explanation for the role of calpain activation and AR proteolysis caused by triptolide should be taken with caution, due to the limitation of data from only one cell line." (PMID 30344270, 2018). "Our pan-cancer analysis of 33 TCGA cancer types revealed broad variability in AR activity, with highest observed in prostate adenocarcinoma." (PMID 41486951, 2026). "Treatment-induced neuroendocrine prostate cancer (NEPC) represents a lethal evolution of prostate adenocarcinoma under androgen receptor pathway inhibition, posing a significant clinical challenge." (PMID 41142932, 2025). "Here, we found Class 1-driven prostate adenocarcinomas faithfully recapitulate key features of primary human PCa, including showing robust AR expression and sensitivity to androgen deprivation upon castration." (PMID 40570057, 2025). "In PCa tissues, MUC1 protein was significantly overexpressed in advanced tumors with NED, compared to localized hormone-naïve prostate adenocarcinomas, while showing decreased AR immunoscore." (PMID 40610411, 2025). "TMPRSS2:ERG gene fusion (T:E fusion) in prostate adenocarcinoma (PCa) puts ERG under androgen receptor–regulated (AR-regulated) TMPRSS2 expression." (PMID 41321318, 2025).
prostate adenocarcinoma (continued). "In prostate adenocarcinomas, BRD4 associates with AR and is recruited to AR target genes, thus activating AR signaling pathways for growth and survival of adenocarcinoma cells." (PMID 40370549, 2025). "Neuroendocrine prostate cancer is an aggressive and increasingly recognized resistance phenotype arising in advanced prostate adenocarcinoma, particularly after prolonged androgen receptor-directed therapy." (PMID 41573423, 2025). "The AR + /NE− subtype encompasses a typical, canonical AR-driven prostate adenocarcinoma, while AR-low/NE− reflects tumors with attenuated but still present AR signaling." (PMID 40593552, 2025). "AR expression was also largely preserved, in line with its reported sensitivity (94.8%) and specificity of about 81.4% for prostatic adenocarcinoma." (PMID 41463218, 2025). "Metastatic biopsy studies have identified mechanisms of lineage plasticity that downregulate the AR-driven luminal prostate adenocarcinoma and upregulate NEPC, but this process exists on a spectrum." (PMID 39859392, 2025). "Our study identifies OPRK1, a G protein-coupled receptor, as a critical mediator of lineage switching from AR+ prostate adenocarcinoma to NEPC." (PMID 41353213, 2025). "It has also been shown to be a potent pure AR antagonist that prevents the binding of synthetic androgen methyltrienolone to both the mutant prostate adenocarcinoma LNCaP AR and the wild-type AR." (PMID 39598525, 2024). "The vast majority of cases of NEPC are thought to be clonally derived from prostate adenocarcinoma and are therefore diagnosed in patients previously treated with hormone therapy and AR pathway inhibitors." (PMID 39682746, 2024). "Although ADT initially suppresses tumor growth by targeting androgen receptor (AR) signaling, a significant proportion of prostate adenocarcinomas (AdPC) develop resistance to ADT, progressing to castration-resistant prostate cancer (CRPC)." (PMID 39711570, 2024). "Since AR signaling appears to be important for prostate development, blocking the AR pathway is anticipated to start the process of converting prostate adenocarcinoma into neuroendocrine tumors." (PMID 38920635, 2024). "The articles generally agree on prostatic adenocarcinomas being the most commonly AR positive cancer entities but published data on AR expression in other tumor entities vary considerably." (PMID 38790919, 2024). "Further, early research revealed that prostate adenocarcinoma cells cultured in an androgen-depleted medium downregulate the expression of AR and its canonical target gene, PSA, and simultaneously acquire an NE phenotype." (PMID 39682746, 2024). "Most of the importance of AR comes from its well-proven role as a highly suited therapeutic target for adenocarcinomas of the prostate." (PMID 38790919, 2024). "Androgen receptors (AR) such as P63 or P40 possess increased sensibility and specificity for prostatic adenocarcinoma, both low-grade and high-grade, and are less expressed in urothelial carcinomas." (PMID 39336523, 2024). "The TCGA database revealed that the AR is highly expressed in prostate adenocarcinoma (PRAD) tissues compared with normal samples." (PMID 38474045, 2024). "All patients had pathologically confirmed prostate adenocarcinomas displayed by HE and nuclear AR immunohistochemical analysis." (PMID 38704600, 2024). "Another study employed ST-seq to analyze AR pathway-positive prostate adenocarcinoma (ARPC) tissues and found that AR marker genes were significantly overexpressed in the ARPC region." (PMID 39470950, 2024). "The third PDX, J000077451 (The Jackson Laboratory), was derived from the brain metastasis of grade IV prostate adenocarcinoma and expressed high levels of AR RNA." (PMID 38546787, 2024). "A set of genetic alterations has been described to be involved in initiation of prostate adenocarcinomas, e.g., mutations of SPOP1 or FOXA1, loss of RB1, fusion of TMPRRS2 and ERG or aberrant activation of the androgen receptor (AR)." (PMID 38704600, 2024).
prostate adenocarcinoma (continued). "Immunohistochemically, 22Rv1 tumors showed a strong nuclear positivity for AR, resembling a prostate adenocarcinoma." (PMID 38704600, 2024). "CWR-R1ca is an androgen-sensitive cell line that expresses the androgen receptor and is known to be highly aggressive, metastatic, and castration-resistant phenotype of human prostate adenocarcinoma." (PMID 37414961, 2023). "In this article, we review the role of various transcription factors (TF) and chromatin modifiers that play a role in lineage reprogramming of prostate adenocarcinomas to NEPC under the selective pressure of various AR-targeted therapies." (PMID 36711033, 2023). "LYC inhibits the proliferation and AR expression of LnCaP cells (androgen‐sensitive human prostate adenocarcinoma cells)." (PMID 37070131, 2023). "Our prior work identified lysine-specific demethylase 1 (LSD1; KDM1A) as a key driver promoting AR-independent survival of prostate adenocarcinoma (PRAD) cells." (PMID 37440313, 2023). "In this article, we review the role of important transcription factors and chromatin modifiers that are instrumental in lineage reprogramming of prostate adenocarcinomas to NEPC under the selective pressure of various AR-targeted therapies." (PMID 36711033, 2023). "ADT is effective because all prostatic adenocarcinomas rely on androgen receptor (AR)-dependent signalling for proliferation." (PMID 36674949, 2023). "The rising prevalence of neuroendocrine prostate cancer (NEPC) is generally thought to be due to use of androgen receptor (AR) signaling inhibitors in treatment of prostate adenocarcinoma." (PMID 36428741, 2022). "Signaling through the androgen receptor (AR) is the primary oncogenic driver of prostate adenocarcinoma." (PMID 36194476, 2022). "Many of these therapies are proficient at targeting the androgen receptor, whose signaling axis is a primary driver of cellular proliferation in prostate adenocarcinoma." (PMID 36317631, 2022). "These NLS genes positively correlate with classical NE makers such as NSE, SYP, and CHGA and negatively correlate with AR and AR target genes in small-cell neuroendocrine group compared with prostate adenocarcinoma." (PMID 36159187, 2022). "For HSPC, the parental genes were mostly enrichment in cell component and metabolic related process, presumably because the distinct metabolic aberrations in prostate adenocarcinoma driven by the androgen receptor (AR)." (PMID 36088396, 2022). "AR is essential for prostate adenocarcinoma cell viability and proliferation and androgen-deprivation therapy (ADT) is therefore used as a first-line treatment to control tumor growth." (PMID 35963852, 2022). "Enhanced miR-34a downregulates AR, forming a positive feedback loop for AR signaling in prostate adenocarcinoma and NEPC cells." (PMID 35447888, 2022). "Androgen receptor (AR)-mediated signalling is essential to maintain the luminal epithelial phenotype of prostate adenocarcinoma." (PMID 36230562, 2022). "In order to evaluate the contribution of WNT4/TCF7L1 to the malignant progression of human prostate adenocarcinomas, AR-positive C4-2 and LNCaP cells stably expressing TCF7L1 were treated with the WNT4 protein." (PMID 34799554, 2021). "POSTN and NETO1 were correlated with androgen receptor expression, a main driver of prostate adenocarcinoma progression." (PMID 34133324, 2021). "AR signalling is crucial for the unique metabolic program of the prostatic epithelium and prostate adenocarcinoma." (PMID 34262149, 2021). "It shows that dihydrotestosterone (DHT) results in the AR-dependent suppression of AC016745.3 expression in the LNCaP androgen-sensitive human prostate adenocarcinoma cell line." (PMID 34833084, 2021). "A significantly higher intensity of staining of AR was found in the case of prostate gland adenocarcinoma than in benign prostate gland hyperplasia." (PMID 33808541, 2021).
prostate adenocarcinoma (continued). "Similar observations were made in CRPC, where adenocarcinoma of the prostate treated with inhibitors of the androgen receptor (AR) switches to a tumor with neuroendocrine phenotype." (PMID 33297508, 2020). "In contrast, neuroendocrine prostate cancer (NEPC) is a highly aggressive form of PCa, that rarely arises de novo and most often emerges from prostate adenocarcinoma after androgen deprivation or androgen receptor (AR) targeted therapy." (PMID 32252342, 2020). "This “neuroendocrine prostate cancer” (NEPC) or CRPC-NE is a subtype of PC that develops mainly via neuroendocrine transdifferentiation of prostate adenocarcinoma in response to AR inhibition therapy." (PMID 33297508, 2020). "F was effectively internalized and visualized by LSCM in LNCaP (AR+) cells (androgen‐sensitive human prostate adenocarcinoma cells overexpressing androgen receptor) after 4 h of incubation when applied at 20 μM." (PMID 32347622, 2020). "In AR-expressing human prostate adenocarcinoma cells, the forced expression of FAS promotes soft agar growth and tumor formation." (PMID 32093357, 2020). "LNCaP is an androgen-dependent cell line that was first isolated from a human metastatic prostate adenocarcinoma in the lymph node and expresses mRNA/protein of both AR and PSA." (PMID 31940946, 2020). "It develops mainly via NE transdifferentiation of prostate adenocarcinoma in response to androgen receptor (AR)-inhibition therapy." (PMID 32512818, 2020). "In prostate adenocarcinoma, the androgen receptor (AR) is a hormone-responsive nuclear receptor transcription factor that coordinates anabolic processes to enable tumor proliferation through transcriptional regulation of metabolic pathways." (PMID 32708919, 2020). "The target of ADT is the transcription factor androgen receptor (AR), which mediates terminal differentiation of luminal epithelium in benign prostatic tissue, but drives cell proliferation in prostatic adenocarcinoma." (PMID 32054861, 2020). "Recent studies have shown that both luminal and basal-type progenitor/stem cells can generate prostate adenocarcinomas, which in most cases exhibit a predominant luminal phenotype with AR positivity and dependency on androgen stimulation." (PMID 31936761, 2020). "When we compared these t-SCNC cases with the prostate adenocarcinoma cases, we observed different accessibilities for the TFs AR, HOXB13, NKX3-1, and GRHL2." (PMID 31604930, 2019). "Compared to the pan-cancer cohort, 83% of prostate adenocarcinoma (PRAD) express elevated AR, reflecting their tissue of origin." (PMID 30053901, 2018). "USP22 controls androgen receptor (AR) accumulation and signaling, and is a predictor of androgen deprivation therapy in prostate adenocarcinoma." (PMID 28567015, 2017). "The LNCaP cells expressed the prostatic specific antigen (PSA) and androgen receptor (AR), with features characteristic of prostatic adenocarcinoma." (PMID 28061438, 2017). "Additional studies have reported androgen-independent early human prostate adenocarcinoma cells and prostate CSCs with low AR." (PMID 27378372, 2016). "AR belongs to the nuclear receptor superfamily and plays an important role in the physiology of normal prostate gland and progression of prostate adenocarcinoma (PRAD)." (PMID 27623747, 2016). "A similar phenomenon was described previously that testosterone decreases AR mRNA but increases AR protein in human prostate adenocarcinoma (LNCaP) cells." (PMID 26008782, 2015). "CA-HPV-10 is an AR-positive PCa cell line derived from a prostatic adenocarcinoma of Gleason Grade 4/4 transformed by transfection with HPV18 DNA9." (PMID 26318033, 2015).
prostate adenocarcinoma (continued). "Histological and immunohistochemical evaluation of DLP tissue from 20-month-old Olfm4-knockout mice revealed that the tumor type that developed in the Olfm4-knockout mice was androgen receptor (AR)-positive prostatic adenocarcinoma." (PMID 26581960, 2015). "Like the normal prostatic glands that develop, regenerate, and function under the influence of androgens, prostatic adenocarcinoma (thereafter adeno-PC) also relies on androgens working through the androgen receptor (AR) for its development and progression." (PMID 24724054, 2014). "While highly proliferating luminal cancer cells are generally positive for AR and PSA, neuroendocrine cells in prostate adenocarcinoma are usually quiescent and lack expression of AR and PSA." (PMID 23852643, 2013). "Because androgen-dependance is a typical characteristic of prostate adenocarcinoma, we sought to determine the behavior of cells under conditions of inhibited androgen receptor (AR) signaling." (PMID 22022528, 2011). "Human prostate adenocarcinoma has a mature luminal phenotype distinguished by androgen receptor (AR) expression and androgen-dependent survival." (PMID 22022528, 2011). "In this study, we constructed and analyzed a mathematical model of the integration between hormone growth factor signaling, androgen receptor activation, and the expression of cyclin D and Prostate-Specific Antigen in human LNCaP prostate adenocarcinoma cells." (PMID 20126616, 2010). "Prostatic adenocarcinomas are dependent on androgen receptor (AR) activity for growth and progression, and therapy for disseminated disease depends on ablation of AR activity." (PMID 18007998, 2007). "In adenocarcinoma of the prostate, AR has been demonstrated by IHC with considerable heterogeneity in staining." (PMID 17020615, 2006). "Collectively, our data clearly demonstrate the importance for EZH2 catalytic function to govern expression/action of MR-TFs that drive phenotypic plasticity and cell state transitions allowing prostate adenocarcinoma evolution to NEPC to evade AR signaling inhibitors." (PMID 40832297, 2025). "To further explore the potency and specificity of 1ae and EPI-001 on the AR-driven transcriptional program, we used RNA sequencing (RNA-seq) on LNCaP prostate adenocarcinoma cells after treatment with approximately IC10 and IC50 doses of the compounds for 6 or 24 h." (PMID 38049566, 2023). "Recent studies suggest that there may be spectrum of cellular differentiation states as AR+ prostate adenocarcinomas evolve to AR-independent NE states." (PMID 35447888, 2022). "All PDXs are typical prostatic adenocarcinoma expressing androgen receptor (AR) and PSA." (PMID 35563856, 2022). "To determine the clinical relevance of these findings, we performed similar scRNA-seq based approaches on a clinical sample isolated from a patient at New York-Presbyterian Hospital/Weill Cornell Medicine who presented with AR-positive prostate adenocarcinoma and AR-negative NEPC liver metastasis." (PMID 34099734, 2021). "In addition to the translocation of AR from the cytoplasm to the nucleus in cells, the mitochondrial distribution of endogenous AR has been demonstrated in human sperm, prostate adenocarcinoma cells, and skeletal muscle cells." (PMID 34180022, 2021). "We first asked whether, similar to TMPRSS2, ACE2 was also regulated by AR signaling in the human prostate adenocarcinoma cell line originally derived from a lymph node metastasis (LNCaP), which is AR expressing and androgen responsive." (PMID 34045511, 2021).